FOXA1 (forkhead box A1)
Diseases named in the same sentence as FOXA1 in open-access papers (continued):
Sharing a sentence is not in itself a finding about the gene and the disease.
breast carcinoma (continued). "Previous studies demonstrated that both FOXA1 and SPDEF are required for proliferation of ZR751 ER+ breast cancer cells." (PMID 27997592, 2016). "This suggests that proliferation of the ER+ breast cancer cell lines was dependent on SPDEF and FOXA1 activity." (PMID 27997592, 2016). "GATA3 and FOXA1 act as pioneer factors essential for mammary morphogenesis, and GATA3 is required for estradiol stimulation of cell cycle progression in breast cancer cells." (PMID 27833659, 2016). "We have found and validated novel modulators of FOXA1 and SPDEF, both of which are of special interest in breast cancer." (PMID 27997592, 2016). "FOXA1 is thought to be a positive regulator of TOX3 expression, mediated by binding to an upstream enhancer, and knockdown of FOXA1 in a breast cancer cell line decreased TOX3 expression." (PMID 25632947, 2015). "Here, we show that in breast cancer MCF-7 cells, TLE3, a co-repressor of the Groucho/Grg/TLE family, interacts with FoxA1 and is detected at regulatory elements of ERα target genes in absence of estrogen." (PMID 25223786, 2014). "We also manually verified these important regulatory TFs in breast cancer cells in literature, such as AP-1, AP-2, C/EBP, E2Fs, ER, FoxA1, Oct-1, NF-κB and others." (PMID 24564526, 2014). "A number of genome-wide analyses have revealed that estrogen receptor α binding to and regulation of its target genes correlate with binding of FOXA1, a pioneer factor, to nearby DNA sites in MCF-7 breast cancer cells." (PMID 24288367, 2014). "Given that TLE3 interacts with FoxA1 and that both factors are important in cancer development, we investigated their role in the MCF-7 breast cancer cell line." (PMID 25223786, 2014). "We find that gene expression patterns within early neoplasias are distinct from both normal and breast cancer patterns and identify a pattern of pro-oncogenic changes, including elevated transcription of ERBB2, FOXA1, and GATA3 at this early stage." (PMID 24887547, 2014). "FOXA1 is co-expressed with ERα and GATA3 and appears to be related to the luminal subtype A in breast cancer." (PMID 24792166, 2014). "First, the cis-regulatory elements for HSF, TEF-1, and C/EBPα and β were statistically enriched at genomic RU486/PR-targets in uterine leiomyoma, whereas E2F, FOXO1, FOXA1, and FOXF sites were preferentially enriched in breast cancer cells." (PMID 22272226, 2012). "STAT1-/- ERα+ mammary tumors also showed elevated transcription of genes characteristic of luminal breast cancers (for example, keratin 8, keratin 18, XBP1, GATA3, MYB, AREG, and FOXA1)." (PMID 22264274, 2012). "Most importantly, STAT1-/- mammary tumors express elevated levels of ERα, PR, GATA3, AREG, XBP1, and FOXA1, all of which are regulated by the transcriptional control of ERα." (PMID 22264274, 2012). "Studies in human breast cancer cells suggest that p400-mediated deposition of H2A.Z at the estrogen receptor alpha-regulated gene, TFF, recruits FoxA1 to facilitate gene expression upon estrogen signaling." (PMID 21785598, 2011). "For example, in human breast cancer cell lines, RAR binding is highly coincident with the binding of estrogen receptor (ER)α, FoxA1, and Gata3, and FoxA1 is required for RAR recruitment." (PMID 21232103, 2011). "A cohort of ERα-negative patients was therefore studied in order to evaluate the predictive importance of FOXA1 and GATA-3 expression in this subset of breast carcinomas." (PMID 19549328, 2009). "In the present study we provide an immunohistochemical approach studying FOXA1 and GATA-3 expression, in order to predict the tumour behaviour of breast cancer patients." (PMID 19549328, 2009). "Scanning the signatures in these genomic assays against the ten features used in our ‘normal’ vs. ‘cancer’ model yielded: two genes in common with Prosigna (FOXA1, MMP11), one gene with OncotypeDX (MMP11), one gene with HER2DX (NEK2), and one gene with Breast Cancer Index (NEK2)." (PMID 41048341, 2025).
breast carcinoma (continued). "To test our hypothesis, we initially analyzed the acetylation of FOXA1 in ER+ (MCF-7) and ER-negative (MDA-MB-453) breast cancer cell lines." (PMID 41224124, 2025). "Furthermore, FOXA1 and XBP1 genes have been identified as key biomarkers across all breast cancer subtypes except Basal-like subtype." (PMID 40468582, 2025). "A search was conducted to answer the question, "What is the prognostic value of FOXA1 expression in breast cancer, estrogen receptor negative?" using various databases." (PMID 41118384, 2025). "Additionally, genes related to mammary gland development, such as FOXA1, TBX genes, and WNT genes, displayed significantly elevated cfNuc signals, suggesting cell type-specific enrichment of cfNuc in breast cancer samples." (PMID 41225146, 2025). "In both hormone-dependent breast and prostate cancers, FOXA1 forms a triumvirate with a GATA protein and an NR (GATA3 and ER in breast cancer; GATA2 and AR in prostate cancer) and is the foundational protein in these cancers due to its ability to create new enhancer elements." (PMID 41168397, 2025). "Additionally, we provide mechanistic data explaining the differential regulation of FOXA1 by HER2 and ER in breast cancer cells." (PMID 41224124, 2025). "The absence of FOXA1 staining in these carcinoma cells supported the finding that the growth of the triple-negative TSG101-induced mammary tumor cells was likely not controlled by steroid hormones." (PMID 40624726, 2025). "Some papers reported that FOXA1 is highly expressed in ER-breast cancers, but we were not able to find this in the BT-549, MDA-MB-231, and MDA-MB-468 TNBC cell lines." (PMID 39000600, 2024). "FOXA1 not only inhibits the molecular phenotype of basal breast cancer cells but also activates the transcription of E-calmodulin and p1Kip51 to block EMT and cell proliferation in basal breast cancer." (PMID 38605023, 2024). "Finally, we show that core FOXC1 targets in TNBC are regulated in parallel by the pioneer factor FOXA1 and the nuclear receptor NR2F2 in ER + breast cancer." (PMID 39171293, 2024). "Our study suggested that FOXA1 may serve as a novel biomarker for HRD, warranting further exploration for its potential in predicting breast cancer HRD in future clinical applications." (PMID 39440050, 2024). "Our AR RIME data is consistent with these MDA-MB-453 studies but does not rule out an interaction between AR and FOXA1 in the other breast cancer models." (PMID 38317241, 2024). "FOXP1, FOXA1, and FOXM1 may be used as potential biomarkers to predict the prognosis of patients with breast cancer." (PMID 38608123, 2024). "FOXA1 protein was highly expressed in only hormone-receptor-positive breast cancer (HR+ BC) cell lines but not in the TNBC cell lines." (PMID 39000600, 2024). "FOXA1 functions as a pioneer factor for ER, promoting luminal-lineage proliferation, whereas GRHL2 is known to be involved in reprogramming ER signaling in breast cancer development." (PMID 38429368, 2024). "As FOXA1 had the most significant gene expression, we checked the correlation between FOXA1 and other diabetes-related genes such as PAK4, FGFR3, MTA3, and KIF22 using a database containing 3262 ER+/PR+ breast cancer patient tissue samples." (PMID 39000600, 2024). "Notably, A485 exposure has also demonstrated the ability to downregulate estrogen receptor protein levels in breast cancer, and EP300/CREBBP acetyltransferase inhibition curtails estrogen signaling through FOXA1-bound enhancers." (PMID 38564048, 2024). "Like GATA3, FOXA1 is a known ER interacting protein in breast cancer, but unlike GATA3, FOXA1 is essential for ER to bind DNA." (PMID 38317241, 2024). "Moreover, we observed a significant negative correlation between POU4F1 expression and master transcription factors of ER positive breast cancer, such as ESR1, FOXA1 and GATA3, in breast cancer patients from the TCGA and METABRIC cohorts." (PMID 38491910, 2024).
breast carcinoma (continued). "FOXA1 is located in the cytoplasm of many tumor cell lines, not only in the breast cancer cell line MCF-7." (PMID 39440050, 2024). "For the prognostic roles of FOXA1 in breast cancer, the results were quite different with positive (high expression of FOXA1 related to a better prognosis), or negative associations." (PMID 37568077, 2023). "Another study, by scATAC-seq of 12 breast cancer patients, found that the transcription factor GRHL2 cooperates with FOXA1 to initiate endocrine resistance and that epigenetic heterogeneity may contribute to endocrine resistance in breast cancer patients." (PMID 37821906, 2023). "Based on the published interaction of GRHL2 with ER⍺, FOXA1, and GATA3 at enhancer elements of target genes, we addressed to what extent the identified conserved GRHL2 binding sites in luminal breast cancer cells were flanked by putative binding sites for the ER⍺-mediated transcriptional complex." (PMID 36691073, 2023). "Notably, previous studies found that the prognostic roles of FOXA1 could be affected by other factors, such as androgen receptor (AR) status, and the combined marker of FOXA1 and AR was found as superior predicting marker of the prognosis compared to the single FOXA1 or AR in breast cancer." (PMID 37568077, 2023). "Like FOXA1, GRHL2 may act as a pioneer factor, promoting chromatin accessibility and GRHL2 has been found to co-occupy enhancer elements with FOXA1, GATA3, and ER⍺ to regulate ER⍺ signaling output in hormone receptor positive breast cancer." (PMID 36691073, 2023). "Furthermore, FOXA1 and MLPH upregulate the expression of luminal-like genes, and both have emerged as prognostic indicators for breast cancer." (PMID 38020889, 2023). "According to the literature, TFF3 acts as an oncogene because it regulates other genes (FOXA1, HER2, and AR) involved in EMT, thus promoting invasiveness, survival, and increased proliferation in multiple carcinomas such as gastric cancer, mammary carcinoma, and prostate cancer." (PMID 37900178, 2023). "FOXA1-BSG association occurred in luminal (luminal A and B) and HER2-positive (non-basal) breast cancer cell lines, in which BSG protein abundance is low relative to basal cell lines." (PMID 35839778, 2022). "In similar, MTX, Etoposide, Fulvestrant, and Resveratrol could suppress the expression of FOXD1, FOXA1, FOXM1, and FOXP1, respectively, which exhibited oncogenic potential in LGG, PRCA/breast cancer, LUAD/LUSC, and PAAD." (PMID 36292640, 2022). "FOXA1 upregulation induced genome-wide enhancer reprogramming and activated the HIF-2α expression and a prometastatic transcriptional program in endocrine-resistant breast cancer." (PMID 35498155, 2022). "Our data show that the expression of POLR3G in breast cancer samples was negatively correlated with that of eight out of ten genes (GATA3; XBP1; AGR2; SIDT1; AR; SPDEF; FOXA1; MLPH) in a list of signature genes most differentially expressed in luminal A compared to basal-like tumors." (PMID 36497214, 2022). "Of further interest is the fact that the correlation between high mean expression of JAM-A, HER2 and FOXA1 and poor patient survival in specifically HER2-positive patients is not limited to breast cancer, but also holds true for HER2-positive gastric cancer patients." (PMID 35203384, 2022). "Herein, we review principal roles of FOXA1 in normal and neoplastic tissues, with special attention to its prognostic and predictive role in luminal and non-luminal breast cancers." (PMID 36230619, 2022). "We selected FOXA1 and evaluated the impact of its expression in the MCF-7 breast cancer cell line." (PMID 35440061, 2022). "Both FOXA1 and GATA3 TFs are known markers in breast cancer." (PMID 35331302, 2022). "It has been reported that the TF network composed of estrogen receptor alpha (ESR1), FOXA1, and GATA3 may control the gene expression pattern in luminal breast cancer." (PMID 34249704, 2021).
breast carcinoma (continued). "There is growing evidence suggesting that FOXA1 has a role independent of ER and other nuclear receptors in breast cancer." (PMID 34680352, 2021). "RNA levels of both factors are much lower than those of FOXA1 in breast cancer, and neither are positively correlated with ESR1 expression." (PMID 34831189, 2021). "There are also reports of SAHA promoting EMT through the HDAC8/FOXA1 axis in triple-negative MDA-MB-231 and BT-549 breast cancer cells, in which SAHA upregulated the mesenchymal markers N-cadherin, vimentin, and fibronectin and downregulated E-cadherin expression." (PMID 34502112, 2021). "FOXA1 and GATA3 have been shown to be consistently expressed in the luminal subtype of breast cancer, indicating the presence of a co-modulatory loop that might contribute to the maintenance of the luminal phenotype." (PMID 34094972, 2021). "As FOXA1 governs the estrogen-regulated transcriptome and cell growth in breast cancer, it is unsurprising that FOXA1 is required for estrogen-induced cyclin D1 (CCND1) expression, cell cycle progression, and proliferation of luminal breast cancer." (PMID 34680352, 2021). "However, the TFs such as KLF5 (52%), KLF1 (39%), and SMAD2::SMAD3::SMAD4 (31%) showed significant enrichment (q < 0.1) in gained peaks and FOX family of TFs (FOXA1 28%, FOXA2 28% and FOXF2 17%) in lost peaks in breast carcinomas." (PMID 34090364, 2021). "ESR1, FOXA1, GATA3, and EP300 TFBSs were enriched in CCVs for overall breast cancer." (PMID 34439109, 2021). "However, the enrichment for ESR1, FOXA1, and GATA3 was stronger for ER-positive CCVs than for ER-negative or overall breast cancer CCVs." (PMID 34439109, 2021). "Particularly, among the top 14 TFs, four (SR1, FOXA1, FOXC1, MYBL2) were among the TFs of the PAM50 gene signature (p = 1.46E-7, hypergeometric test), further indicating their role in regulatory mechanisms of breast cancer subtypes." (PMID 33558504, 2021). "Other NRs also play critical roles in breast cancer progression, such as vitamin D receptor, and liver receptor homolog-1; however, these NRs function independent of FOXA1 for chromatin access." (PMID 34680352, 2021). "Together, FOXA1 and GRHL2 induce the expression and activity of LYPD3, a Ly6 receptor family member, as well as its ligand AGR2, in mouse models of endocrine resistant breast cancer, as well as patient tumors that progressed on endocrine therapy." (PMID 34680352, 2021). "Using breast cancer cell and tissue models and culminating in patient tissue material, we provide evidence that JAM-A regulates HER3 expression via a pathway involving the transcription factors β-catenin and FOXA1." (PMID 33669586, 2021). "A subclass of TNBC known as “molecular apocrine” cancers are defined by coexpression of AR and FOXA1 as well as a luminal breast cancer signature, despite lacking ER expression." (PMID 34680352, 2021). "A similar result was obtained when using a six-gene (AGR2, SLC44A4, TBC1D9, FOXA1, GATA3, and CA12) breast cancer steroid response module (Kruskal-Wallis p = 0.01 across all patients, p = 0.94 in HRDetect-high patients, and p = 0.02 in HRDetect-low/intermediate patients)." (PMID 33568222, 2021). "To test putative links between JAM-A, FOXA1 and HER3, we first examined whether FOXA1 expression levels in breast cancer cells were sensitive to manipulation of JAM-A levels." (PMID 33669586, 2021). "Interestingly, we found a novel co-regulation of FOXA1 and GATA3 with a common binding partner of AP-1 complex like breast cancers that appears to drive activity of distal enhancers, but not promoters." (PMID 33858483, 2021). "Reduction of SPRY4 expression, for example, increases cancer stem cell properties in MDA-MB-231 cells, while reduced expression of FOXA1 and GATA3 by inhibiting the mitogen-and stress-activated protein kinase (MSK1) enhances the metastatic progression of ER + breast cancer." (PMID 34238359, 2021).
breast carcinoma (continued). "While the role of FOXA1 in resistance to traditional chemotherapy has not been explored in breast cancer, FOXA1 drives cell cycle progression in chondrosarcoma, a malignant bone tumor highly resistant to chemotherapy." (PMID 33417085, 2021). "Our study suggested that a FOXA1 and DSCAM-AS1 loop might be important for tumor growth of lung adenocarcinoma and breast cancer." (PMID 32929382, 2020). "This may be reason for the high expression of DSCAM-AS1 in some ER- breast cancer cell lines, such as SKBR3 and MDA-MB-453, which have been reported as FOXA1 positive cells." (PMID 32929382, 2020). "Forkhead box protein A1 (FOXA1; also known as hepatocyte nuclear factor 3α or HNF3A), was originally identified as a transcriptional activator in liver development and is expressed in breast cancer." (PMID 31562808, 2019). "FOXA1 plays a crucial role in the regulation of luminal differentiation and is not expressed in the basal subtype of breast cancer." (PMID 31013830, 2019). "Here, we show FOXA1 expression in breast cancer metastases, but it is still unclear whether other FOXA family members such as FOXA2 and FOXA3 also play a role in breast cancer." (PMID 30819139, 2019). "Over 80% of FOXA1 and GATA3-positive breast carcinomas belonged to the luminal A subtype." (PMID 30819139, 2019). "In breast cancer samples B7 and B13, we detected in concordance with the ATAC-seq data increased accessibility for GRHL2, FOXA1, and ZNF121, a zinc finger protein, which was recently implicated in regulation of cell proliferation and breast cancer development." (PMID 31604930, 2019). "No studies have investigated the prognostic value of FOXA1 and Nestin expression in breast cancer metastases." (PMID 30819139, 2019). "Further inspection of the modules found that three of these modules are related to known breast cancer related processes such as epithelium development, chromosome organization, and mitotic cell cycle including well-known breast cancers genes such as NCOA3, AURKA, MKI67, and FOXA1." (PMID 30906311, 2019). "Using SAGE and GEPIA, we found that the expression level of FOXA1 is significantly higher in breast cancer tissues than in normal breast tissues." (PMID 31562808, 2019). "The last known subtype, luminal androgen receptor (LAR), is found to overlap with the molecular apocrine group (“molecular apocrine breast cancer”/MABC) and is enriched in genes regulating hormone signaling, in particular androgen signaling and synthesis (AR, FOXA1, KRT18, XBP1)." (PMID 30871273, 2019). "FOXA1 is already included in PAM50, which is also a gene profiling kit for breast cancer patients." (PMID 30819139, 2019). "In breast cancer, GRHL2 has previously been shown to directly interact with FOXA1, which may contribute to the tethering of the histone methyltransferase MLL3 and, consequently, epigenetic marks at GRHL2/FOXA1 binding sites." (PMID 31084623, 2019). "Together these data suggest that bladder and breast cancer do not harbor the distinctive indel signature observed 3′ of the FOXA1 forkhead domain in prostate cancer." (PMID 30272002, 2018). "Of those, FOXA1, ESR1 and GATA3 are not only reported as co-expressed and co-localized in breast cancer cells, but there is even strong evidence suggesting they might form an enhanceosome that regulates many genes involved in the ER signaling cascade." (PMID 29741575, 2018). "The AR is able to induce HER2/HER3 dimerization through FOXA1 (Forkhead box protein A1) in the HER2 enriched ERα-negative breast cancer cells." (PMID 28474005, 2017). "We apply for the first time genome-wide expression–methylation quantitative trait loci (emQTL) analysis between DNA methylation and gene expression, and discover that DNA methylation at enhancers and ERα, FOXA1, and GATA3 binding regions is a breast cancer subtype-specific phenotypic feature." (PMID 29123100, 2017).